GDF15 (growth differentiation factor 15)
Diseases named in the same sentence as GDF15 in open-access papers (continued):
Sharing a sentence is not in itself a finding about the gene and the disease.
liver fibrosis (continued). "Although GDF15 has been related to chronic liver diseases, including some aspects of MASH such as hepatic fibrosis and liver stiffness, the potential relationship between circulating levels of GDF15 and key features of MASLD predisposing to atherosclerotic CV disease has not been fully explored." (PMID 40076667, 2025). "Furthermore, in individuals with advanced fibrosis, GDF-15 levels were even higher, and GDF-15 overexpression was found to induce phosphorylation of fibrosis-related factors in HSCs, thereby promoting liver fibrosis and accelerating NAFLD progression." (PMID 41333917, 2025). "Furthermore, we observed that impaired clearance of GDF-15 in STAB-1−/−-STAB-2−/− mice contributed to severe glomerular fibrosis and mild perisinusoidal hepatic fibrosis." (PMID 39000420, 2024). "This strongly predictive character for hepatic fibrosis was exclusively observed for GDF15 but not for ANGPTL4, CCL5, GPNMB, and IGFBP6." (PMID 36430499, 2022). "Consistently, in this study, serum GDF15 levels were significantly higher in patients with cirrhosis than in those without cirrhosis, and serum markers of hepatic fibrosis showed a relatively strong positive correlation with serum GDF15 levels." (PMID 35610317, 2022). "ROC curve analysis confirmed that GDF15 represents an excellent marker for the discrimination of individuals with advanced hepatic fibrosis (NFS > 0.76; n = 14) and without hepatic fibrosis (NFS < −1.455; n = 64) at study base-line (AUC = 0.910)." (PMID 36430499, 2022). "Serum GDF-15 levels can significantly differentiate between chronic HCV patients with liver fibrosis and healthy controls, and also can discriminate between early and advanced liver fibrosis." (PMID 34777864, 2021). "Therefore in the current study, we tested for the first time panel of serum markers of liver fibrosis, including PLGF, GDF15, and HGF." (PMID 28301573, 2017). "GDF‐15 correlated with hepatic dysfunction (MELD Spearman's ρ: 0.50; albumin ρ: −0.57), HVPG (ρ: 0.47), systemic inflammation (C‐reactive protein ρ: 0.45; interleukin 6 [IL‐6] ρ: 0.55; procalcitonin ρ: 0.58), liver stiffness (ρ: 0.67) and enhanced liver fibrosis test (ρ: 0.64) (all p < 0.001)." (PMID 41555670, 2026). "Importantly, serum GDF15 levels for each liver disease were further compared in patients with non-cirrhosis to eliminate the effects of liver fibrosis." (PMID 35610317, 2022). "Based on our results from ROC curve analysis, a serum GDF15 concentration of 415.41 pg/mL might be suggested as a cut-off value for discrimination of advanced hepatic fibrosis versus the absence of fibrosis." (PMID 36430499, 2022). "Finally, although liver fibrosis is a critical aspect of NAFLD progression, we were unable to test the causal relationship between GDF-15 and fibrosis outcomes due to the lack of publicly available GWAS data on NAFLD fibrosis stages, which represents an important avenue for future research." (PMID 41333917, 2025). "Additionally, research by Peng Qi indicated that GDF-15 plays a profibrotic role in liver fibrosis in mice via the TGF-β/Smad2/3 pathway, proposing that inhibiting GDF-15 may serve as a viable treatment approach for alleviating fibrosis and delaying HSC activation." (PMID 41333917, 2025). "In addition to liver fibrosis, our findings that GDF-15 concentrations were significantly increased in patients with NAFLD and T2DM compared to those without T2DM, are consistent with various previous studies indicating that GDF-15 concentrations are increased in patients with T2DM." (PMID 34663793, 2021). "However, it is not known whether circulating GDF-15 concentrations are potentially involved in the known relationship between T2DM and liver fibrosis in patients with NAFLD." (PMID 34663793, 2021).
ovarian carcinoma (32 papers, 2012 to 2025). A malignant neoplasm originating from the surface ovarian epithelium. "GDF-15 was further reported to predict the failure of platinum-based chemotherapy and proposed as a diagnostic biomarker in ovarian cancer." (PMID 32508832, 2020). "This disruption destabilizes the POLR2A protein, resulting in the inhibition of GDF15 transcription and a significant reduction in GDF15 expression and secretion in ovarian cancer cells." (PMID 39899667, 2025). "This disruption suppresses GDF15 expression and secretion, highlighting a novel regulatory mechanism in ovarian cancer cells." (PMID 39899667, 2025). "CCK8 assays revealed that GDF15 knockdown significantly impaired the proliferation of ovarian cancer cells, while transwell assays showed that GDF15 knockdown inhibited cell migration and invasion in both MDAH2774 and TOV112D cells." (PMID 39899667, 2025). "In line with our findings, GDF15 promotes the immune escape of ovarian cancer by targeting CD44 in dendritic cells." (PMID 36776876, 2023). "A three-marker panel of GDF-15, IL-6, and IL-6 R alpha was initially identified to differentiate primary or recurrent ovarian cancer from healthy controls." (PMID 37357306, 2023). "In MyD88-positive type I epithelial ovarian cancer cells, GDF-15 induced NF-κB signaling in vitro, thereby up-regulating stemness markers (OCT-4, SOX-2) and chemokine expression (CXCL-1, IL-8, and MCP-1)." (PMID 32508832, 2020). "In ovarian cancer, elevated GDF-15 was identified as an independent predictor for poor progression-free and overall survival, even after correction for FIGO stage and age (p = 0.01)." (PMID 32508832, 2020). "This allowed us to interrogate the gene expression changes in both A2780 ovarian cancer cells (human) and stromal cells (mouse) by GDF15 knockdown and cisplatin treatment." (PMID 33086658, 2020). "Stromal GDF15 has also been identified by others to be involved in the malignancy of ovarian cancer." (PMID 33086658, 2020). "A previous ovarian cancer study showed that GDF15 expression was higher in post-chemotherapy than in pre-chemotherapy effusions." (PMID 33086658, 2020). "In this study, we showed that GDF15 expression is induced in ovarian cancer cells by treatment with the chemotherapeutic agent cisplatin both in vitro and in vivo." (PMID 33086658, 2020). "Using our orthotopic mouse model of ovarian cancer in which GDF15 was knocked down enabled us to look at GDF15 from two angles: its role in ovarian tumorigenesis and its effect following treatment with cisplatin." (PMID 33086658, 2020). "To determine the role of GDF15 in the response of ovarian cancer to treatment with cisplatin, we generated stable GDF15-KD A2780 cell lines using two different shRNAs targeting GDF15." (PMID 33086658, 2020). "The hormone GDF-15 has been reported to be overexpressed in various types of cancer including prostate, breast and ovarian cancer." (PMID 30646851, 2019). "The Youden’s Index of GDF15 in the diagnosis of ovarian cancer is 0.736 at the 519.6 pg/mL clinical reference value by the ROC curve, and the sensitivity and specificity of GDF15 in diagnosis ovarian cancer were 85.3% and 88.3%." (PMID 29580231, 2018). "These Akt and Erk pathways have also been reported to induce cell growth by GDF15 in esophageal and ovarian cancers." (PMID 27903972, 2017).
ovarian carcinoma (continued). "It had been reported that GDF15 stimulated ovarian cancer cell growth and invasion through AKT/mTOR and MAPK signaling." (PMID 28199981, 2017). "It is therefore of high medical interest to further elucidate GDF15-dependent signaling networks and the prognostic value of GDF15 in patients with ovarian cancer with regard to the development of carboplatin resistance." (PMID 25490861, 2015). "N-(4-hydroxyphenyl)-retinamide (4HPR) treatment of A2780 ovarian cancer cells can induce PLAB/GDF15 upregulation via a ROS-dependent mechanism." (PMID 23799024, 2013). "However, further investigation is needed to elucidate the specific molecular mechanisms through which GDF15 promotes ovarian cancer development." (PMID 39899667, 2025). "Further, GPx3’s regulation of GDF15 expression could enhance ovarian cancer immune therapies by targeting extracellular GPx3 or GDF15." (PMID 41009046, 2025). "In other tissues, similar redox–SMAD interactions are at play: in ovarian cancer, GPx3 helps maintain levels of GDF15 (a TGF-β family member) and supports tumor growth, whereas knocking down GPx3 in ID8 cells lowers GDF15, delays ascites onset, and markedly reduces omental tumors in mice." (PMID 41009046, 2025). "However, a recent report showed that levels of circulating GDF15 correlated with chemoresistance of ovarian cancer patients to platinum therapy." (PMID 35626166, 2022). "Several of these proteins have been described in the literature as mediators of ovarian cancer progression, including associations of their expression in tumor tissue or blood or ascites levels with ovarian cancer survival, for instance IL-6, GDF15, OPN/SST1, PVRL4, and VEGFA." (PMID 31737572, 2019). "For examples, GDF15 possesses pro-tumorigenic functions, as indicated by the high expression or secretion in many types of cancer tissues, including colorectal, gastric, esophageal, oral, pancreatic, liver, and ovarian cancers." (PMID 27903972, 2017). "We previously found that GDF15 induces EMT in ovarian cancer cells." (PMID 29212236, 2017). "The concordant findings showed an increase in GDF15 expression in irradiated oral cancer cells, an increase in plasma GDF15 levels in chemotherapeutic-resistant testicular cancer patients, and increased sensitivity to chemo-drug treatment after GDF15 knockdown in a mouse model of ovarian cancer." (PMID 27903972, 2017). "In summary, we showed that GDF15 might serve as a novel treatment target in women with platinum-resistant ovarian cancer." (PMID 25490861, 2015). "Based on previous studies which showed a correlation between high plasma GDF15 and poor treatment response in ovarian cancer patients, we measured the GDF15 plasma concentration following short- and long-term carboplatin treatment in A2780 and A2780cis tumor-bearing mice." (PMID 25490861, 2015). "Because ErbB2 was reported to be expressed in chondrocytes and GDF15 was observed to interact with this receptor in ovarian cancer, we demonstrated that this interaction was conserved in chondrocytes and may have partially explained the mechanism of the GDF15/MAPK14 signaling pathway." (PMID 35806043, 2022). "To further investigate the role of GDF15 in ovarian cancer, we designed specific siRNAs to knock down GDF15 in MDAH2774 and TOV112D ovarian cancer cells." (PMID 39899667, 2025).
ovarian carcinoma (continued). "It has been shown that SNHG2 can block the transcription of CCAAT/enhancer binding protein β (CEBPB)-mediated growth differentiation factor 15 (GDF15), further leading to the apoptosis of ovarian cancer cells." (PMID 41200835, 2025). "This suggests that ovarian cancer has a direct effect on the kidney’s function, as the tumor led to increase in expression levels of IL-1β, TNFα, IL6, and GDF-15." (PMID 39394174, 2024). "GDF15 overexpression stimulates PI3K/Akt/mTOR and MEK/ERK signaling, and promotes epithelial to mesenchymal transition (EMT) in colorectal and ovarian cancer cells." (PMID 29212236, 2017). "Targeting the circMETTL6/NONO/GDF15 axis presents a potential therapeutic avenue for ovarian cancer treatment." (PMID 39899667, 2025). "Some combinations of these biomarkers such as HE4, osteopontin (OPN), and GDF-15 along with CA-125 seem promising, but still lack of sufficient sensitivity or specificity for early detection of recurrent ovarian cancer." (PMID 37357306, 2023). "In this study, we evaluated a panel of 8 biomarkers, including B7-H3, IL-6, PLA2G7, Tie-2, GDF-15, IL-6 R alpha, sSDC1, and VCAM-1 selected based on their reported relevancy to ovarian cancer and multiplexing feasibility as a customized magnetic bead-based 8-plex immunoassay." (PMID 37357306, 2023). "In this study, we found GDF15 levels to be highly enhanced during carboplatin treatment in the platinum-sensitive ovarian cancer model A2780 but not in the platinum-resistant model A2780 in vivo." (PMID 25490861, 2015). "Additionally, we show that GDF15 overexpression can reverse the inhibitory effects of circMETTL6 overexpression or NONO knockdown on ovarian cancer cell proliferation and migration." (PMID 39899667, 2025). "Targeting the circMETTL6/NONO/GDF15 axis may offer valuable insights for prognosis and therapeutic strategies in ovarian cancer." (PMID 39899667, 2025). "Interestingly, in patients with ovarian cancer serum levels of GDF-15 levels were not higher in the patients with malignant neoplasms." (PMID 30646851, 2019). "Restoration of GDF15 expression can rescue the inhibited cell proliferation and metastasis caused by circMETTL6 overexpression, underscoring the critical role of circMETTL6 in disrupting NONO/POLR2A‐mediated GDF15 upregulation and subsequent ovarian cancer progression." (PMID 39899667, 2025). "GDF15 transcription was similarly reduced by circMETTL6 overexpression and NONO knockdown in ovarian cancer cells." (PMID 39899667, 2025). "Mechanistic studies revealed that circMETTL6 inhibits ovarian cancer progression by recruiting the NONO protein, disrupting its interaction with POLR2A, and subsequently suppressing GDF15 transcription." (PMID 39899667, 2025).
pulmonary fibrosis (29 papers, 2015 to 2026). Chronic progressive interstitial lung disorder characterized by the replacement of the lung tissue by connective tissue, leading to progressive dyspnea, respiratory failure, or right heart failure. "The published studies showed that the inflammatory cytokines of GDF-15 and leptin were associated with infections, metabolism, and lung fibrosis." (PMID 35784345, 2022). "It has been reported that GDF15 is associated with multiple organ fibrosis such as atrial, renal, and pulmonary fibrosis." (PMID 33178828, 2020). "Taken together, our data suggest that GDF15 is directly linked to lung fibrosis and may play a role in cell senescence." (PMID 35993367, 2022). "Determining the nature of GDF15's role in pulmonary fibrosis will be crucial to elucidating how GDF15 may be used alone or in combination as a diagnostic, prognostic biomarker, or both." (PMID 33344478, 2020). "Additionally, the study showed that elevated GDF15 levels in the blood may precede pulmonary fibrosis development, and may mediate the association between aging and interstitial lung abnormalities." (PMID 33344478, 2020). "Previous research on idiopathic pulmonary fibrosis, utilising single‐cell RNA sequencing, has revealed that epithelial cells are a major source of GDF15." (PMID 41474228, 2026). "A recent study has shown that imperatorin, a naturally occurring furanocoumarin derivative, ameliorates lung fibrosis by stimulating GDF15 secretion in fibroblasts." (PMID 40565178, 2025). "GDF15 expression was upregulated in bleomycin-induced lung fibrosis model following the induction of senescence in alveolar epithelial cells and macrophages." (PMID 40565178, 2025). "For example, increased GDF15 in idiopathic pulmonary fibrosis (IPF) promotes fibrosis via fibroblast activation and collagen deposition." (PMID 40565178, 2025). "In bleomycin-induced lung fibrosis in mice, increased GDF15 secretion by senescent alveolar cells exerts pro-fibrotic effects by activating fibroblasts and macrophages." (PMID 40565178, 2025). "During lung fibrosis, GDF15 secreted by the senescent alveolar type II epithelial cells promotes EMT of these cells via autocrine signaling through TGF-β receptors." (PMID 40565178, 2025). "In vivo, GDF15 neutralization in a BLM‐induced lung fibrosis model significantly alleviated lung fibrosis." (PMID 41409095, 2025). "In vivo studies, particularly using bleomycin-induced lung fibrosis models, demonstrated that GDF15 neutralization reduced collagen deposition and attenuated fibrotic development." (PMID 40565178, 2025). "The role of GDF15 in the progression of lung fibrosis has been emphasized in multiple recent studies in humans and experimental animal models." (PMID 40565178, 2025). "One study found that GDF-15 expression and accumulation are increased in the extracellular matrix of idiopathic pulmonary fibrosis." (PMID 38672115, 2024). "The expression of the GDF15 protein is significantly increased in both the circulation and tissues of patients suffering fibrotic diseases, such as idiopathic pulmonary fibrosis (IPF), cardiac fibrosis, and systemic sclerosis." (PMID 39643709, 2024). "For instance, GDF15 promotes the activation and differentiation of lung fibroblasts, particularly contributing to the progression of idiopathic pulmonary fibrosis." (PMID 38392243, 2024). "In a bleomycin-induced lung fibrosis mouse model, GDF-15 expression and protein levels are increased in the lung tissue, bronchoalveolar fluid, and plasma of mice with pulmonary fibrosis." (PMID 39000420, 2024). "GDF15 levels were quantified by ELISA in HP (n = 64), idiopathic pulmonary fibrosis (n = 54), and healthy control (n = 128) groups." (PMID 38195721, 2024). "In our study, we demonstrated by the first time, that the levels of circulating GDF15 were increased in HP compared with controls, but more importantly, this increase was mostly related to the presence of lung fibrosis." (PMID 38195721, 2024).